TNF (tumor necrosis factor)
Diseases named in the same sentence as TNF in open-access papers (continued):
Sharing a sentence is not in itself a finding about the gene and the disease.
type 2 diabetes (continued). "C-reactive protein levels were not affected by n-3 supplementation (3 g/day for eight weeks) in a randomized control trial for persons with type 2 diabetes; yet IL-2 and TNF-α, other indicators of inflammation, were reduced in the n-3 group." (PMID 31667003, 2013). "TNF-α contributes to the pathogenesis of diabetic retinopathy, and significantly higher levels of TNF-α are found in the plasma of patients affected by either type 1 or type 2 diabetes versus age-matched healthy control subjects." (PMID 23365614, 2013). "Others report that aerobic exercise training decreases plasma CRP, TNF-α and IL-18/IL-10 ratios in type 2 diabetics." (PMID 24324580, 2013). "In subjects with poorly controlled type 2 diabetes who lost weight rapidly, with lower levels of BMI and leptin, levels of TNF-α were reported to be higher than in controls." (PMID 24260344, 2013). "In a GK rat model of type 2 diabetes, treatment with IL-1 receptor antagonist (IL-1Ra) reduced islet mRNA expression of a number of inflammatory factors which includes: IL-1β, IL-6, TNF-α, MCP-1 and MIP-1α." (PMID 24359406, 2013). "It has been reported that patients with type 2 diabetes have 3-4 times greater serum levels of TNF-α, compares to healthy control." (PMID 23862164, 2013). "In conclusion the present study suggested that in type 2 diabetic patients, increased hs-CRP, TNF-α, uMCP-1, and SAA were associated with DN pathogenesis." (PMID 24350298, 2013). "KBG has a favorable effect on impaired glucose metabolism in type 2 diabetes by improving glucose intolerance, and it has been suggested that some of these effects are derived from the reduction of the TNF-α content in skeletal muscle." (PMID 23213558, 2012). "Systemic levels of proinflammatory cytokines, including TNF-α, IL-1β, and IL-6, are elevated in patients with both type 1 and type 2 diabetes." (PMID 23320034, 2012). "Keywords used in the search were combinations of the “diet,” “chronic inflammation,” “type 2 diabetes,” “C-reactive protein,” “interleukins,” and “tumor necrosis factor” (TNF)." (PMID 23316349, 2012). "The analysis of the plasma cytokine profile of patients with type 2 diabetes showed that pro-inflammatory cytokine levels were increased, although only the levels of IL-8, IL-12, and TNF-α were significantly increased when compared to healthy volunteers." (PMID 22500980, 2012). "Regarding inflammatory biomarkers (IL-6 and TNF-α), type 2 diabetes patients had higher levels compared with NGT subjects." (PMID 23251434, 2012). "Further, increased levels of AGP1 reflect elevated levels of cytokines, such as interleukin-1 (IL-1), IL-6, and tumor necrosis factor alpha (TNF-α), which are associated with type 2 diabetes." (PMID 22536212, 2012). "CD33 expression was significantly decreased in monocytes from patients with type 2 diabetes, and higher levels of TNF-α, IL-8 and IL-12p70 were detected in the plasma of patients compared to healthy donors." (PMID 22500980, 2012). "Based on the previous studies and our results, we concluded that TNF-α promoted fgl2 expression in glomerular and tubulointerstitial endothelial cells of rats with type 2 diabetes." (PMID 23554679, 2011). "Enzyme linked immunosorbent assays (ELISA) additionally showed that circulating TNF-α levels in rats with type 2 diabetes were significantly elevated and closely correlated with fgl2 expression (r = 0.871, P < 0.01)." (PMID 23554679, 2011). "At the 19th, 23rd and 28th week of the experiment, circulating TNF-α concentration in rats with type 2 diabetes was significantly higher than that of normal rats and showed an increasing tendency." (PMID 23554679, 2011). "In our study, levels of TNF-α in rats with type 2 diabetes were significantly elevated and were closely related to fgl2 expression." (PMID 23554679, 2011).
type 2 diabetes (continued). "There has been no systematic evaluation of the association between genetic variants of type 2 receptor for TNFα (TNFR2) and type 2 diabetes, despite strong biological evidence for the role of this receptor in the pathogenesis of this complex disorder." (PMID 21849023, 2011). "TNF-α and IL-6, incidence of known hypertension, and type-2 diabetes were significantly greater among AMI patients compared to healthy subjects." (PMID 20671994, 2010). "In vivo, the decrease in circulating TNF-α level has been reported to be involved in improvement of β-cell function of type 2 diabetic patients receiving transient intensive insulin therapy." (PMID 21113299, 2010). "In contrast to IL-6 and TNF-α, adiponectin mRNA is reduced in adipose tissue from patients with type 2 diabetes." (PMID 20671994, 2010). "The anti-diabetic agent, pioglitazone, has been reported to decrease TNF-α and increase serum adiponectin in type 2 diabetic patients." (PMID 19114996, 2008). "In the present study, we have demonstratedthat in type 2 diabetes, there is an increased mRNA expression of resistin,along with significant increases in TNF-α, IL-6, and Il-1β mRNA expression bythe peripheral circulating mononuclear cells." (PMID 19125180, 2008). "Type 2 diabetes is characterised by increased plasma concentrations of pro-inflammatory cytokines [such as tumour necrosis factor – alpha; TNF-α] and soluble forms of adhesion molecules involved in leukocyte – endothelial interactions." (PMID 17714581, 2007). "Ectodomain shedding by ADAM proteinases is highly relevant in view of the well described but unexplained increase in circulating soluble adhesion molecule concentrations and TNF-α in Type 2 diabetes." (PMID 17714581, 2007). "Circulating levels of inflammatory cytokines such as IL-6 and TNFα are increased in type 2 diabetes." (PMID 16787541, 2006). "The TNF induced DBC1 and SIRT1 pathway may be an important pharmacological target to improve metabolic disorders, such as type 2 diabetes, fatty liver disease, and diseases with known associations between inflammation and metabolism." (PMID 40766326, 2025). "Decreases serum levels of IL-1β and TNF-α in patients with type II diabetes mellitus." (PMID 41141350, 2025). "In patients with type 2 diabetes, serum TNF-α levels are higher than in the control group." (PMID 40904859, 2025). "A final group of five biomarkers (CXCL9, IL-2RB, MMP-10, STAMBP, TNF-α) showed positive associations with changes in CES-D in people with type 2 diabetes but without significant effect modification (pinteraction ≤ 0.18)." (PMID 40624224, 2025). "Furthermore, quercetin has been reported to modulate MSC inflammation by reducing the production of TNF-α and the secretion of various inflammatory cytokines in MSCs derived from patients affected by type 2 diabetes and impaired glucose tolerance." (PMID 40621132, 2025). "Furthermore, another study found a significant link between increased AAR and the levels of inflammatory cytokines such as IL-4, IL-6, and TNF-α in type 2 diabetes." (PMID 40408358, 2025). "In addition, dry eye disease is highly prevalent among patients with type 2 diabetes and has been consistently linked to increased tear concentrations of proinflammatory cytokines such as IL-6, CXCL8, and TNF-α." (PMID 41030257, 2025). "Moreover, inflammatory biomarkers such as CRP and TNF-α seem to be predictors for type 2 diabetes and some cardiovascular events." (PMID 38257152, 2024). "In conclusion, elevated IL-18, NFATC4, TNF-α, and IL-6 levels suggest inflammation is key in prediabetes pathogenesis, highlighting the need for further research into interventions to delay or prevent type 2 diabetes." (PMID 40027364, 2024).
type 2 diabetes (continued). "In order to explore in more depth the inflammatory process that occurs in type 2 diabetes, we measured the levels of inflammation markers TNF-α, ICAM-1 and MPO in serum, and compared the leukocyte–endothelium interactions in type 2 diabetic participants with those in healthy participants." (PMID 38981930, 2024). "A comprehensive meta-analysis examining the relationship between serum TNF-α levels and diabetic peripheral neuropathy in patients with type 2 diabetes revealed increased TNF-α levels in patients with diabetic neuropathy compared to those without neuropathy and controls." (PMID 38673830, 2024). "Clinical studies have shown that the daily consumption of beetroot juice in patients with type 2 diabetes mellitus, for a 12-week period, reduced the concentrations of inflammatory markers, including IL-6, TNF-α, and NF-κB, which are involved in the pathogenesis of complications of type 2 diabetes." (PMID 39682981, 2024). "In addition to Aβ accumulation, previous studies illustrated an increase in levels of proinflammatory cytokines such as IL-1β, IL-6, and TNF-α in patients with type 2 diabetes." (PMID 38510866, 2024). "Genetic variations in the promoter region of the TNF-α gene may regulate TNF- α production, transcription and affect susceptibility to or protection from inflammatory-related diseases such as malaria and type 2 diabetes." (PMID 37215099, 2023). "Studies have demonstrated high levels of TNF-α in patients with type 2 diabetes." (PMID 37215099, 2023). "Interestingly, the TNF-α-induced inflammation seen in malaria infection is similar to that observed in type 2 diabetes." (PMID 37215099, 2023). "Haus and colleagues were among the first to compare the levels of ceramide species in the circulation of patients with type 2 diabetes to those in healthy controls and to determine whether they correlate with insulin sensitivity and plasma TNF concentrations." (PMID 37762318, 2023). "Visceral white adipose tissue (abdomen and upper body) appears to be the major source of inflammatory markers in type 2 diabetes (cytokines, TNF-alpha, IL-1, IL-6, IL-10, leptin, adiponectin, monocyte chemoattractant protein, angiotensinogen, resistin, chemokines, etc.)." (PMID 37298118, 2023). "Likewise, the direct administration of safranal for four weeks significantly reduced the circulating levels of interleukin 1β and TNF-α in an experimental model of type 2 diabetes in rats." (PMID 37627614, 2023). "Two clinical studies reported increased serum levels of anti-inflammatory cytokines (IL-4 and IL-10) and decreased levels of TNF-α, IFNγ, IL-12, and IL-6 in females with type 2 diabetes who received 8 weeks of daily NUTRIOSE® supplementation (10 g/day) versus baseline levels." (PMID 37836513, 2023). "The pertinent question then, is, how does TNF-α connect malaria and type 2 diabetes?" (PMID 37215099, 2023). "Several studies have demonstrated high levels of TNF- α in patients with type 2 diabetes." (PMID 37215099, 2023). "The top 13 signal pathways according to the number of genes mainly include: tumor-related signal pathway, MAPK signal pathway, TNF signal pathway, liver cancer signal pathway, type II diabetes-related signal pathway, lactation signal pathway, FcεR I signal pathway and IL-17 signal pathway." (PMID 35879791, 2022). "Furthermore, among those with detectable S1-reactive CD4+T cell responses, the frequency of polyfunctional CD4+T cells which co-produced IFNγ and TNFα was also significantly lower in participants with type 2 diabetes (p=0.005)." (PMID 36304475, 2022). "Besides that, adropin administration in streptozotocin-induced type 2 diabetic rats decreased TNF-α levels." (PMID 35897011, 2022).
type 2 diabetes (continued). "The model of Type 2 diabetes in db/db mice is characterized by increased expression of TNF-α in the spleen, underexpression of IL-10 in the liver and spleen, an elevated number of PMNs in peripheral blood (a sign of inflammation), and diminished expression of chitinases in the liver and spleen." (PMID 35330193, 2022). "Evidence indicate that inflammation and, in particular, high levels of TNF-α, IL-β and IL-6 are factors involved in the development of type-1 diabetes, and TNF- α, IL-1, IL-6, IL-10, leptin, and adiponectin are the factors involved in the development of type-2 diabetes." (PMID 36011116, 2022). "IL-6, together with TNF-α, are molecules that can trigger pathophysiological processes related to common comorbidities, such as type 2 diabetes, systemic arterial hypertension and endothelial damage, among others; however, an important comorbidity to consider is neuroinflammation." (PMID 36290695, 2022). "A direct consequence of this event is the increased production of cytokines, including IL-6 and TNFα, which interferes with the normal transmission of the insulin signaling favoring the onset of type 2 diabetes and further propagating the state of chronic inflammation." (PMID 34769261, 2021). "A study conducted in patients with type 2 diabetes found that consuming CEO causes a significant reduction in fasting blood glucose (FBS), glycosylated hemoglobin (HbA1c), and serum levels of insulin, adiponectin, and TNFα." (PMID 34769261, 2021). "Curcumin could improve endothelial function and reduce oxidative stress and levels of inflammatory markers (IL-6, TNF alpha, endothelin-1) in type 2 diabetes patients and enhance the functions of β cells." (PMID 34069726, 2021). "Additionally, plasma levels of C-reactive protein (CRP), tumor necrosis factor-α (TNF-α), and interleukin-6 (IL-6) are elevated in subjects with type 2 diabetes, indicating the existence of low-grade systemic and hyperglycemia-induced inflammation." (PMID 33536442, 2021). "In this regard, the L14 extract might have therapeutic potential for type 2 diabetes by activating the insulin signaling pathways following TNF-α reduction." (PMID 33954196, 2021). "TNF-α is upregulated in the adipose tissue of patients with cancer and type 2 diabetes." (PMID 34502316, 2021). "Therefore, further researches are needed to have a broader vision about cinnamon intake on plasma level of NF-kB, SIRT1 and systemic inflammation factors including hs-CRP, IL-6 and TNF-α in type 2 diabetes patients." (PMID 31901246, 2020). "Elevation of IL‐6 during exercise induces an anti‐inflammatory environment by inducing the production of IL‐1ra and IL‐10, and also inhibiting TNF‐α production; subsequently abating the chronic systemic low‐grade inflammation seen in cardiovascular disease, Type 2 diabeters, and muscle wasting." (PMID 31407867, 2020). "After 30 days of treatment, B. vernae extract significantly decreased the serum levels of fasting blood glucose, insulin, insulin resistance index, glycated serum protein, TNF-α, IL-1β, and IL-6, whereas significantly increased the serum levels of insulin sensitivity index in type 2 diabetic rats." (PMID 32636751, 2020). "Our results are consistent with the generally accepted hypothesis that TNF plays an essential role in the development of IR and type 2 diabetes." (PMID 33138337, 2020). "Our results may indicate that IR and type 2 diabetes development may be exacerbated by the accumulation of TNF-α and IFN-γ in a deprived environment." (PMID 32299896, 2020). "Hesperidin and naringin lowered the level of pro-inflammatory cytokine (tumor necrosis factor-alpha (TNF-α) and interleukin (IL)-6) production and enhanced antioxidant defenses in a type 2 diabetes rat model by normalizing the altered blood glucose and antioxidant parameters in the liver." (PMID 32977511, 2020).
type 2 diabetes (continued). "As a result, our study elucidated that the cinnamon supplementation in the way of three grams per day for 8 weeks has not remarkable effect in reduction of NF-kB, SIRT1, hs-CRP, IL-6 and TNF-α plasma levels which have key role in atherogenicity in type 2 diabetes patients." (PMID 31901246, 2020). "For instance, eight weeks of 84% dark chocolate supplementation along with therapeutic lifestyle changes guidelines reduced inflammatory markers (high-sensitivity C-reactive protein (hs-CRP), tumor necrosis factor-alpha (TNF-α), and interleukin-6 (IL-6)) in type 2 diabetic patients." (PMID 33007981, 2020). "Also, plasma TNF-α concentration was increased in type-2 diabetic subjects and correlated with increased C18:1 and C18:0 Cer subspecies." (PMID 31031634, 2019). "Pro-inflammatory molecules (e.g., TNF, IL-6, IL-1β) are increased in type II diabetes and AD, which may compromise the hippocampal insulin receptor expression and/or signaling." (PMID 31291963, 2019). "During the development of type 2 diabetes, activated macrophages in the adipose tissues increased secretion of TNF-α expression, which induced the production of several inflammatory cytokines, hormones and their receptors and controls the mechanisms that induce metabolic stress." (PMID 30974824, 2019). "In conclusion, this study found that urinary Tf, IgG, NGAL, and TNF-α levels may be used as biomarkers for the diagnosis of early-stage DN in patients with type 2 diabetes." (PMID 31218128, 2019). "If type 2 diabetes is a clinical state of inflammation with high levels of cytokines such as TNFα and these levels can be reduced by certain anti-inflammatory drugs, why these cannot be used as another component of our treatment strategy for this common disease?" (PMID 29576769, 2018). "In addition, miR-296-3p can reduce the resistance of αTC1–6 cells to apoptosis induced by cytokines, such as IFN-γ, IL-1β and TNF-α, suggesting its involvement in the regulation of Type 2 diabetes." (PMID 30134788, 2018). "Presumably, TNFα reduces the activity of insulin, which may lead to the development of type 2 diabetes." (PMID 30383538, 2018). "TNF-α also has been associated with aseptic activation of inflammasome NLRP3 which mediates several major chronic diseases including arteriosclerosis, type 2 diabetes and Alzheimer disease." (PMID 29541394, 2018). "Additionally, GZFLW has a favorable effect on impaired glucose metabolism in type-2 diabetes by improving glucose intolerance, and it has been suggested that some of this effect is derived from the reduction of TNF-α content in skeletal muscle." (PMID 30037150, 2018). "Accordingly, we hypothesized that LncNONRATT021972 could be a potential biomarker for neuropathic pain of type 2 diabetes in the clinical scenario, and TNF-α was a potential downstream factor under regulation of LncNONRATT021972." (PMID 28928602, 2017). "However, the coma time following acute ammonia intoxication was significantly increased after challenge with TNFα." (PMID 28801579, 2017). "What is more, increased LncRNA NONRATT021972 could aggravate neuropathic pain via activating TNF-α-related pathways in patients with type 2 diabetes." (PMID 28928602, 2017). "In one mouse model of Type 2 Diabetes (T2DM) pre-treatment with oleic acid reversed the inhibitory effects of TNFα on insulin production, while in vivo, oleic acid-treated cells resulted in elevated translocation of the PPAR-activated receptor transcription factor to the nucleus." (PMID 27531998, 2016). "Furthermore, various longitudinal studies have shown that elevated levels of CRP, IL-1β, IL-6, and TNF-α predict the development of type 2 diabetes." (PMID 27034691, 2016). "Both type 1 and type 2 diabetes are associated with increased blood concentrations of several inflammatory biomarkers, including C-reactive protein (CRP), interleukin (IL)-2, IL-6 and tumour necrosis factor-alpha (TNF-α)." (PMID 27544079, 2016).